IL11 (interleukin 11)
Diseases named in the same sentence as IL11 in open-access papers (continued):
Sharing a sentence is not in itself a finding about the gene and the disease.
breast cancer (continued). "Reduced pSTAT3 levels were also observed in the estrogen receptor (ER)‐negative breast cancer cell line, MDA‐MB‐231, confirming the ER independence of the bazedoxifene effect on IL11/gp130 signaling." (PMID 30885958, 2019). "The HNSCC iCAF resided in the IL11 + CAF cluster; this semi-conserved phenotype was one of the most abundant fibroblast subpopulations in HNSCC, colorectal carcinoma (CRC) and oesophageal squamous cell carcinoma (ESCC) but was not present in lung or breast cancers." (PMID 39757146, 2025).
Thrombocytopenia (50 papers, 2008 to 2026). A reduction in the number of circulating thrombocytes. "Most studies on IL-11 have focused on unconventional chemotherapy regimens that cause severe thrombocytopenia." (PMID 40766766, 2025). "Therapeutic targets for managing sepsis-associated thrombocytopenia include IL-11 and recombinant human thrombopoietin, which have shown promising results in improving platelet counts." (PMID 37841241, 2023). "IL-11 proved its effectiveness in treatment of thrombocytopenia; however, it causes adverse events, which limits its use." (PMID 27144685, 2016). "IL-11 has a specific effect on hematopoietic cells, being responsible for platelet production; therefore, recombinant human IL-11 (rhIL-11) has been used as an anti-inflammatory agent to treat chemotherapy-associated thrombocytopenia." (PMID 39274304, 2024). "IL-11 is identified from bone marrow stromal cells at first 29 and developed to treat patients with thrombocytopenia resulted from exposure to chemotherapy." (PMID 41362740, 2026). "Granulocytopenia or agranulocytosis improved with G-CSF or PG-CSF, while thrombocytopenia was alleviated with IL-11, TPO, or oral TPO receptor agonists (TPO-RAs)." (PMID 40809009, 2025). "Interleukin 11 (IL11) was initially thought important for platelet production, which led to recombinant IL11 being developed as a drug to treat thrombocytopenia." (PMID 39383190, 2024). "Thrombocytopenia was ultimately successfully managed using recombinant human thrombopoietin, prednisone, and recombinant human interleukin-11." (PMID 38903494, 2024). "Recombinant human IL11 (rhIL11) is used as a drug to increase platelets in patients with thrombocytopenia but this has severe and unexplained cardiac side effects that were previously believed sporadic and non-specific." (PMID 39383190, 2024). "Il11 administration (Oprelvekin, NeumegaTM) reduces the need for platelet transfusions by approximately a third in severe chemotherapy‐induced thrombocytopenia." (PMID 39361945, 2024). "Ongoing research into platelet production drugs has identified recombinant interleukin-11 as the only FDA-approved drug for chemotherapy-induced thrombocytopenia." (PMID 39065683, 2024). "In an RCT examining IL-11 therapy in patients with thrombocytopenia, a less extensive inflammatory response and lower mortality was observed (31% vs. 14%, n = 105)." (PMID 38807151, 2024). "Due to its initial characterization as a hematopoietic cytokine, the first described IL-11 treatment was rh-IL11, used to reduce thrombocytopenia in chemotherapy patients." (PMID 38392279, 2024). "IL-11 has lymphopoietic/hematopoietic and osteotrophic properties, as it improves platelet recovery after thrombocytopenia and participate in the regulation of bone cell proliferation and bone resorption." (PMID 36769039, 2023). "Earlier studies investigated the effects of IL11 in cancer as a potential treatment for chemotherapy-induced thrombocytopenia among cancer patients." (PMID 35883698, 2022). "The need to determine suitability of IL11 treatment for thrombocytopenia in cancer patients motivated early studies evaluating its effects on cancer cells." (PMID 35883698, 2022). "Subsequently, IL11 was evaluated as a potential therapy for chemotherapy-induced thrombocytopenia among cancer patients." (PMID 35883698, 2022). "In November 2020, the patient developed thrombocytopenia (platelet level: 91×103/ul) with normal hemoglobin and normal white cell counts and received the interleukin-11(IL-11) therapy to enhance the proliferation of megalokaryocytes for 2 weeks." (PMID 34956221, 2021). "Four patients in the TACE-CRA group who suffered from grade 3–4 thrombocytopenia were treated with recombinant human interleukin-11 to assist with recovery." (PMID 32850395, 2020). "Recombinant human interleukin-11 (rhIL-11) is a cytokine that can stimulate thrombopoiesis and is commonly used to treat thrombocytopenia." (PMID 30877597, 2019).
Thrombocytopenia (continued). "Grade 4 adverse reactions occurred in only 1 patient of rh‐endostatin 7d group who developed thrombocytopenia after treatment, and platelet count gradually returned to normal after treatment of megakaryocyte (recombinant interleukin 11)." (PMID 30762300, 2019). "IL-11 was isolated in 1990, and recombinant human IL-11 (rhIL-11) was developed and marketed to reduce chemotherapy-induced thrombocytopenia but its clinical use is limited by the requirement of multiple daily injections and severe adverse effects in humans." (PMID 31956306, 2019). "Recombinant human interleukin-11 (rhIL-11) is currently undergoing a series of clinical trials and is used as a preferred drug to treat chemotherapy-induced thrombocytopenia." (PMID 30877597, 2019). "A possible side effect of blocking IL11Rα in cancers in humans, is the effect on platelet counts, since IL11 is used as a treatment option for thrombocytopenia after chemotherapy." (PMID 28186993, 2017). "Recombinant IL-11 is an efficient cytokine in patients with malignancies who suffered chemotherapy-induced thrombocytopenias." (PMID 27922075, 2016). "In fact, recombinant IL-11 has been approved for the treatment of severe thrombocytopenia by the US Food and Drug Administration." (PMID 27199988, 2016). "IL-11 is the only agent approved by the FDA in the United States to prevent severe thrombocytopenia and reduce the need for platelet transfusion following myelosuppressive chemotherapy for non-myeloid malignancies." (PMID 27144685, 2016). "The pharmacologic blocking of IL-11 signaling in cancer contradicts to clinical application of recombinant human IL-11 (Oprelvekin) for stimulation of bone marrow to prevent chemotherapy-induced thrombocytopenia." (PMID 27916836, 2016). "Reduce movement, control the blood pressure, avoid using antiplatelet drugs, and use interleukin-11 (IL-11) and rhTPO when patients have thrombocytopenia and bleeding." (PMID 25802542, 2015). "IL-11 is a cytokine derived from stromal cells that has multiple effects on thrombocytopenia induced by chemotherapy or bone marrow transplantation (BMT)." (PMID 21619578, 2011). "After RFA, IL-11 was administered subcutaneously at a dose of 3 mg per day because of thrombocytopenia." (PMID 21619578, 2011). "This is evidenced by the fact that thrombocytopenia in cirrhotic patients is not only attributed to hypersplenism due to portal hypertension but also resulted from decreased thrombopoeitin and interleukin-11." (PMID 22087192, 2011). "Interleukin-11 (IL-11) is a pleiotropic cytokine approved by the FDA against chemotherapy-induced thrombocytopenia." (PMID 18941632, 2008). "Thrombocytopenia treatment with interleukin 11 and thrombopoietin was successfully completed." (PMID 39507704, 2024). "WT IL‐11 was approved as a treatment for thrombocytopenia to increase platelet production in 1997,55 thus, ‘super‐agonist’ forms of IL‐11 have potential to be utilized as a more effective alternative that could be pursued." (PMID 38023717, 2023). "Until recently, IL-11 was better known for its capacity to stimulate platelet production, and for decades, cancer patients have been treated with rhIL-11 to overcome CT-induced thrombocytopenia." (PMID 33553157, 2020). "IL-11 is involved in hematopoiesis, especially production of thrombocytes, which led to its approval as the drug ‘Oprelvekin’ for the treatment of chemotherapy-induced thrombocytopenia." (PMID 31357561, 2019). "Because no toxicity was observed after the intravenous administration of H11, this hyper-cytokine may be potentially useful for treatment of thrombocytopenia and other IL-11-dependent disorders." (PMID 27144685, 2016). "However, IL-11 is a megakaryopoietic cytokine that stimulates platelet production, and it has been shown that recombinant IL-11 is an efficient support therapy in patients with malignancies who develop thrombocytopenia as a side effect of chemotherapy." (PMID 27487122, 2016).
Thrombocytopenia (continued). "In addition to TPO, other agents, such as interleukin 1 (IL-1), IL-6, IL-3 and IL-11, have been studied in clinical trials as thrombocytopenia agents." (PMID 27144685, 2016). "Indeed, IL-11 has thrombopoietic activity, and recombinant human IL-11 has been used for thrombocytopenia in clinical settings." (PMID 25946003, 2015). "Interleukin-11 (IL-11) is a promising therapeutic agent for thrombocytopenia." (PMID 21619578, 2011). "Therefore, we choose IL-11 to platelet transfusion, which used to treat thrombocytopenia for preventing life-threatening bleeding episodes in patients with hepatic carcinoma from radiofrequency ablation." (PMID 21619578, 2011). "Therefore, IL-11 was administered subcutaneously at a dose of 3 mg per day because of thrombocytopenia." (PMID 21619578, 2011). "We describe two cases of CLS after IL-11 administration in two males with thrombocytopenia." (PMID 21619578, 2011). "Recombinant human IL-11 was Food and Drug Administration approved in 1997 and marketed as Neumega (oprelvekin, Wyeth Pharmaceuticals) as the first platelet growth factor to treat severe thrombocytopenia or prevent severe thrombocytopenia following chemotherapy." (PMID 38093747, 2023). "Furthermore, the higher potency of macaque IL-11 to STAT3 activation in the genetically modified HEK293 cells could be therapeutically significant in treatment of thrombocytopenia." (PMID 27916836, 2016). "In addition, IL-11 might be crucial in the acute management of certain types of hypersplenic thrombocytopenia in hepatic carcinoma." (PMID 21619578, 2011). "In parallel to more severe thrombocytopenia in Vivaxhigh patients, plasma levels of cytokines inducing megakaryocytic differentiation in the BM, thrombopoietin (TPO), and IL-11 were significantly increased in this cluster." (PMID 34585667, 2021). "Recombinant human (rh) IL-11, a Food and Drug Administration (FDA)–approved drug for treating thrombocytopenia, was initially claimed to be cardioprotective and antifibrotic." (PMID 34516874, 2021). "IL-11 is the only agent approved by USA Food and Drug Administration (FDA) to prevent severe thrombocytopenia and reduce the need for platelet transfusion following myelosuppressive chemotherapy for non-myeloid malignancies." (PMID 22433466, 2012). "IL-11 is used to treat grade 3/4 thrombocytopenia following chemotherapy for solid tumors and non-myeloid leukemia." (PMID 40766766, 2025). "IL-11, the only drug for CIT which is approved by the Food and Drug Administration in the United States, can elevate nadir of platelet count from 40×103/μL to 60×103/μL, while rhTPOs have been reported to elevate nadir (from 20×103/μL to 44×103/μL) and shorten the duration of thrombocytopenia." (PMID 30174705, 2018). "Recombinant human interleukin-11 (rhIL-11, oprelvekin) received FDA approval for the prevention of chemotherapy-induced thrombocytopenia (CIT) in patients with nonmyeloid malignancies." (PMID 36430539, 2022). "At present, the common treatment for thrombocytopenia is divided into non-drug therapy, such as platelet infusion, and drug therapy, such as thrombopoietin receptor ag-onists (TPO-RAs), recombinant human interleukin-11 (rHuIL-11), and recombinant human thrombopoietin (rHuTPO)." (PMID 36430539, 2022).
gastric cancer (45 papers, 2010 to 2026). A primary or metastatic malignant neoplasm involving the stomach. "Although these studies have been correlative, the present study, in which we use a hyperactive gp130 mutant (Gp130FF) gastric cancer mouse model, we demonstrate a causal relationship between gp130/IL-11 signalling and Yap1 function." (PMID 37957015, 2024). "In one study, administration of IL-11 signaling antagonist IL-11-Mutein reduced inflammation-associated colorectal cancer and gastric carcinoma in a mouse model." (PMID 30736824, 2019). "Expression of transcripts encoding multiple pro-inflammatory cytokines previously implicated in gastric cancer was also elevated, including IL-6, IL-11, IL-1β, and TNFα." (PMID 26859571, 2016). "The IL-6 family member IL-11 is a pleiotrophic cytokine, and has elevated expression in association with gastric cancer development." (PMID 25528766, 2015). "In an in vitro co-culture model of gastric cancer cells and cancer-associated fibroblasts where high IL-11 secretion was measured, treatment with an IL-11 neutralizing antibody significantly inhibited JAK/STAT3 activity leading to reduced cell migration and invasion." (PMID 35053592, 2022). "With respect to other cytokines, IL-11 may be associated with gastric cancer, as treatment by IL-11 in mice resulted in chronic atrophic gastritis." (PMID 35892729, 2022). "Also, IL‐11 has a stronger correlation with the progression of sporadic and inflammation‐associated colon and gastric cancers." (PMID 32860492, 2020). "Although IL11 was initially found to be a hematopoietic and inflammatory cytokine, the use of IL11 receptor alpha null mice (Il11ra1KO) has revealed a more prominent role of IL11 compared to IL-6 during the progression of sporadic and inflammation-associated colon and gastric cancers." (PMID 37365574, 2023). "Thus, CAF-derived IL-11 secretion caused resistance to chemotherapy regimens in gastric cancers." (PMID 35326670, 2022). "However, there is little evidence of such aberrations contributing to cancer, although a recent study showed that polymorphisms in IL11 could affect susceptibility to gastric cancer." (PMID 34834425, 2021). "IL-11 receptor alpha is increasingly recognized as an important mediator of gastric cancer progression in humans, where IL-11 signaling promotes epithelial proliferation, inflammation, and fibrosis, and represents a potential therapeutic target (Wang DQ." (PMID 40673273, 2025). "Our work previously demonstrated a strong causal link of gp130 proinflammatory cytokines IL-6, and more so, IL-11 in the development of gastric cancer." (PMID 37957015, 2024). "The increase in IL-11 corresponds to the IL-11 Mutein-PEG in circulation, while immunoglobulins are associated with stromal remodeling in early gastric cancer." (PMID 38542101, 2024). "CAF-induced interleukin 6 (IL-6) and interleukin 11 (IL-11) activate the JAK-STAT3 pathway in gastric cancer (GC) cells." (PMID 35884907, 2022). "Secretion of IL-11 from CAFs activated the IL-11/IL-11R/gp130/JAK/STAT3/Bcl anti-apoptosis signaling pathway in gastric cancer cells." (PMID 35326670, 2022). "Having long been established as a haematopoietic growth factor, research in recent years has highlighted the potential pro-tumourigenic role of IL11 in epithelial cancers, with abundant evidence of its role in gastric cancer." (PMID 34834425, 2021). "IL-11, a member of the IL-6 family, promotes the progression of chronic inflammation to gastric carcinoma via gp130-mediated activation of STAT3 and STAT1 signaling in human gastric carcinogenesis." (PMID 34210998, 2021).
gastric cancer (continued). "Bazedoxifene has also been shown to block STAT3 activation by IL-11 in human cancer cell lines, and reduce the tumor burden in murine models of gastric cancer." (PMID 32765502, 2020). "Mast cells are activated by interleukin (IL)-33, an alarmin produced by the tumor epithelium in response to the inflammatory cytokine IL-11, which is required for the growth of gastric cancers in mice." (PMID 31227713, 2019). "Previous studies have revealed the critical roles of IL-11 in tumorigenesis of liver, colon, and gastric cancers." (PMID 30086773, 2018). "Aberrant expression of IL-11 and its receptor IL-11Rα was found in gastric cancer tissues, and correlated with Lauren’s classification, tumor invasion and vessel infiltration." (PMID 25929737, 2015). "The aim of our study was to dissect the individual contributions of oncogenic signaling mediated by gp130 and IL-1RT1 ligands in IL-11/STAT3 mediated gastric cancer development." (PMID 25528766, 2015). "In present study, IL-11 expression was found related with MTA2 in gastric cancer cells by genome expression analysis, and was validated in both cell models and xenografts tissues." (PMID 25929737, 2015). "Increased expression of IL-11 was found in biopsies from human gastric cancer patients, and IL-11 has been shown to be the critical IL-6 family cytokine in gastric tumor formation." (PMID 24742922, 2014). "We have shown that STAT3 is constitutively activated in human gastric cancer, and that chronic IL-11-driven STAT3 transcriptional activity induces gastric tumourigenesis in the gp130757FF mouse model of gastric cancer development." (PMID 24804649, 2014). "Recently we and others have shown that in gastric tumours, significant increases in transcription coincide with increased expression of the gp130 ligand IL-11 in human gastric cancer and mouse models of this disease." (PMID 24804649, 2014). "In a string of studies using gp130 mutant mouse model of gastric cancer, the importance of IL-11 was highlighted and IL-6 is reported to be relatively unimportant." (PMID 23593346, 2013). "IL-11 has now been identified as a driver in a wide range of malignancies, including breast, prostate, endometrial, ovarian, liver, and gastric cancers, and is considered an important biomarker in determining the prognosis of patients with breast, lung, and gastric cancers." (PMID 38248304, 2024). "Moreover, in gastric cancer and lung adenocarcinoma, CAFs drive chemoresistance through IL-11 secretion via IL-11/STAT3/Bcl2 signaling pathway." (PMID 34095111, 2021). "Ma and his colleagues demonstrated that IL-11 could enhance the chemoresistance of gastric cancer cells by modulating the JAK/STAT3 signaling pathway." (PMID 34149927, 2021). "IL-11 levels are significantly higher in a murine model of gastric cancer, and IL-11 is the major factor that drives STAT3 activation and corresponding inflammation in murine gastric and colon cancer models, as well as human cell line xenograph models of these cancers." (PMID 32765502, 2020). "Given the important role of IL‐11 in gastric cancer, our study may provide an alternative route toward IL‐11 regulation and possible disruption of IL‐11/STAT3 pathway." (PMID 31273847, 2019). "Decreased degradation of IL‐11 mRNA may subsequently augment STAT3 signaling to facilitate gastric cancer development." (PMID 31273847, 2019). "IL-11 is one of the downstream effectors of MTA2 in regulating gastric cancer cells growth." (PMID 25929737, 2015). "The rescue assay suggested that MTA2 promoting gastric cancer cell colony formation might partially through IL-11 as a downstream effector." (PMID 25929737, 2015). "Furthermore, higher levels of IL-11 expression have been reported in distant metastatic gastric cancer cells." (PMID 26528857, 2015). "Therefore, the novel OL8/IL‐11/STAT3 signaling axis may enrich our understanding of mechanisms of gastric cancer progression." (PMID 31273847, 2019).